ENSG00000222588
Synonyms: LOC124900296
Gene: Small nucleolar RNA gene on chromosome 10 (119,060,983 to 119,061,111, reverse strand). Ensembl gene ENSG00000222588.
Gene Ontology:
Biological process: RNA processing
Cellular component: nucleolus
Homologues: Orthologues: mouse Gm54606 (75% identical). Paralogues in human: SNORA19 (71% identical).